GHRH (growth hormone releasing hormone)
Diseases named in the same sentence as GHRH in open-access papers (continued):
Sharing a sentence is not in itself a finding about the gene and the disease.
tumor (continued). "The expression of mRNA for GHRH and the presence of biologically or immunologically active GHRH were demonstrated in several established cancer cell lines and human tumours." (PMID 18506184, 2008). "Collectively, these data suggest that in different human tumors, GHRH and its tumoral receptors might form an autocrine/paracrine mitogenic loop involved in tumor development and progression." (PMID 39934495, 2025). "Despite initial concerns that GHRH agonists might stimulate tumor growth, studies have shown that these compounds may, in fact, inhibit the proliferation of certain cancer types." (PMID 39592529, 2024). "In vitro studies using human lung cancer cell lines, including small-cell lung cancer (SCLC) H446 and non-small-cell lung cancer (NSCLC) HCC827 and H460 cells, demonstrated that GHRH agonist MR-409 exerted significant agonistic activity, inhibiting tumor growth." (PMID 39592529, 2024). "Proteomic studies conducted on tumor cells treated with GHRH agonists have suggested that these compounds may exert their anti-tumor effects by inducing the differentiation of cancer cells." (PMID 39592529, 2024). "Moreover, the surprising anti-tumor effects observed with MR-409 in various cancer models provide new insights into the potential pharmaceutical applications of GHRH agonists in oncology." (PMID 39592529, 2024). "Extensive research has demonstrated that GHRH antagonists exert their antitumor effects by binding to GHRH receptors expressed on tumor cells, thereby blocking GHRH-mediated signaling pathways involved in tumor growth, invasion, and survival." (PMID 39592529, 2024). "However, as research began to show the presence of GHRH and its receptors in various extrahypothalamic tissues, including tumor cells, the possible oncogenic or anti-oncogenic effects of GHRH came under scrutiny." (PMID 39592529, 2024). "Based on the evidence that GHRH antagonists were able to suppress experimental tumor growth and that a subset of EC expressed receptors for GHRH, the application of powerful new GHRH antagonists could be useful for the treatment of this type of malignancy." (PMID 35566020, 2022). "GHRH antagonists (GHRHAnt) were developed to suppress tumor progression and metastasis." (PMID 36540765, 2022). "In malignant cells, GHRH stimulates tumor growth by paracrine and autocrine mechanisms." (PMID 34944669, 2021). "It has been shown that GHRH can be secreted by many extrahypothalamic tissues and tumor cells." (PMID 28032599, 2017). "The syndrome is frequently associated with functioning pancreatic NETs, which most commonly secrete gastrin, glucagon, insulin or pancreatic polypeptide; less frequently tumours which secrete vasoactive intestinal polypeptide or growth hormone releasing hormone." (PMID 28965289, 2017). "It remains to be elucidated whether GHRH specifically affects GSCs and its effects on tumor endothelial cells." (PMID 26977157, 2016). "GHRH and its receptor have been found in many tumor cell lines and neoplasms." (PMID 27774107, 2016). "GHRH may also play a role in the activation of stromal fibroblasts in the tumor microenvironment by regulating α-SMA expression." (PMID 26977157, 2016). "Thus, in addition to modulating GH release, GHRH indirectly regulates the proliferation of cells in multiple other tissues including tumor cells through a GHRH/GH/IGF-1 axis." (PMID 27774107, 2016). "The tumor-inhibitory effect of GHRH antagonists seems to involve complex mechanisms." (PMID 27448980, 2016). "Other contributors that could facilitate the expansion of the somatotroph tumor cells are hypothalamic GHRH or somatostatin, paracrine growth factors, and ghrelin." (PMID 22518126, 2012). "However, much evidence from both in vivo and in vitro experiments shows that GHRH antagonists can also directly suppress tumor cells growth." (PMID 20509930, 2010).
tumor (continued). "GHRH antagonists can suppress tumor growth by indirect and direct pathways." (PMID 20509930, 2010). "The anti-tumour effects of GHRH antagonists can be also mediated through direct mechanisms." (PMID 18506184, 2008). "Originally recognized for its role in regulating growth hormone (GH) secretion, GHRH has since been discovered to exert broader physiological effects beyond the pituitary gland, with GHRH receptors identified in multiple extrahypothalamic tissues, including tumor cells." (PMID 39592529, 2024). "However, GHRH antagonists may be able to suppress the tumor progression by counteracting the localized circuits of GHRH/GHRH-R that are active in the tumor microenvironment." (PMID 27774107, 2016). "IPA (Ingenuity Pathway Analysis) further showed that the hepatic fibrosis signaling pathway, tumor microenvironment pathway, IL-17 signaling, HER-2 signaling and GHRH signaling were activated in Mdr2−/− mice, which were inhibited after BBR treatment." (PMID 38273376, 2024). "GHRH antagonists suppressed cell proliferation and decreased the levels of the proliferation marker, PCNA, in the three cell lines and in PC3 tumor." (PMID 27448980, 2016). "GHRH can stimulate tumor growth through the GHRH/GH/IGF-1 axis and local GHRH stimulatory loops between GHRH and its receptor." (PMID 27774107, 2016). "A definitive diagnosis of ectopic GHRH production can be made either by showing an arteriovenous gradient of GHRH across the tumor bed or by normalization of GHRH, IGF-I, and GH levels after removal of the tumor." (PMID 22518126, 2012). "PanNETs represent a heterogeneous group of tumours, presenting either as hormonally active tumours (producing gastrin, insulin, glucagon, somatostatin, vasoactive intestinal peptide or growth hormone-releasing hormone) or as non-functioning tumours." (PMID 39949334, 2025). "In addition to directly inhibiting tumor cell proliferation, GHRH antagonists reduce the secretion of growth factors such as IGF-1, VEGF, and pro-inflammatory cytokines, which are essential for tumor angiogenesis and metastasis." (PMID 39592529, 2024). "Further evidence demonstrates that the antitumor effect of GHRH antagonists is mediated by the suppression of tumor growth through autocrine/paracrine faction rather than regulating the pituitary-GH-hepatic IGF-I axis." (PMID 28032599, 2017). "Functioning tumours may present due to symptoms of the clinical syndrome (eg ectopic ACTH secretion, GHRH secretion, PTHrP secretion)." (PMID 28965289, 2017). "The GHRH antagonist MZ-J-7-114 was shown to block the activities of VEGF and downregulate the expression of epidermal growth factor (EGF) and VEGF receptors, thereby effectively abolishing angiogenesis and tumor growth." (PMID 27774107, 2016). "Treatment with GHRH antagonists reduced proliferation only in tumor cell lines, without changes in non-tumor cells." (PMID 27448980, 2016). "In fact, <10% of cells from these tumors responded to CRH, LHRH, TRH, and GHRH, with little or no intra-tumor differences." (PMID 26106585, 2015). "The precise role of the production of GHRH in the process of tumorigenesis and tumour progression has not been investigated previously." (PMID 18506184, 2008). "The stimulatory loop formed by GHRH and its receptors can be blocked by GHRH antagonists, which exhibit antitumor functions across various cancer types, by directly inhibiting SV1 signaling or blocking tumor-derived insulin-like growth factor 1 (IGF1) and IGF2." (PMID 40244089, 2025). "Furthermore, it has been proposed that while GHRH analogs of the Miami family can inhibit tumor growth, they do not have a strong endocrine inhibitory effect." (PMID 38588464, 2024).
tumor (continued). "It has been also demonstrated that GHRH and its agonistic analogs display cardioprotective, anti-inflammatory, anxiolytic and antidiabetogenic effects, and promote proliferation, migration and survival in many non-malignant and tumor cell types." (PMID 36232554, 2022). "GHRH displays, among others, strong cardioprotective, anti-inflammatory and anxiolytic functions and also acts as a growth factor through autocrine/paracrine mitogenic mechanisms in both nonmalignant and tumor cells." (PMID 34439107, 2021). "However, growth hormone-releasing hormone (GHRH) agonist MR409 (N-Me-Tyr1, D-Ala2, Asn8, Arg29-NHCH3-JI-38) was demonstrated to suppresses tumor growth of human experimental lung and other cancers, including gastric, pancreatic, urothelial, prostatic, mammary, and colorectal." (PMID 32121443, 2020). "It was found that these GHRH agonists do not stimulate tumor growth or neoplastic transformation." (PMID 27494841, 2016). "In contrast, a few genes (TDGF1, GHRH, and BCL9) reported to be involved in promoting cell proliferation are downregulated which highlights the fact that cellular transformation is a multistage process with a sustained tug of war between tumor suppressor and tumor promoter." (PMID 23216862, 2012). "The absence of expression of GHRH and its receptors in PC-3 tumours after combined treatment may suggest that the observed reduction in tumour growth is a consequence of the modification of the molecular machinery involved in the processes of tumourigenesis, angiogenesis, and metastasis." (PMID 39456984, 2024). "This hypothesis, however, does not exclude a possibility that GHRH agonists may also bind to an unknown homologous G-protein coupled receptor and directly inhibit the IGF-1 production in both hepatic and tumor cells as proposed by Kineman for the actions of GHRH antagonists." (PMID 29983893, 2018).
cancer (52 papers, 2000 to 2025). A tumor composed of atypical neoplastic, often pleomorphic cells that invade other tissues. "GHRH regulates the secretion of GH from the anterior pituitary gland, previously associated with cancer progression and inflammation." (PMID 38895505, 2024). "The presence of GHRH-R and its splice variants—supporting the role of GHRH—has been demonstrated in different cancers, such as esophageal and colorectal neoplasms." (PMID 36979698, 2023). "However, previous investigations have also identified splice variants (SVs) of GHRH-Rs in human cancers and other extrapituitary tissues that can mediate the effects of GHRH and its agonistic and antagonistic analogs." (PMID 39201517, 2024). "Moreover, the expression of GHRH and GHRH-Rs, including the splice variant 1 (SV1) of GHRH-R, has been shown in a variety of cancers, where GHRH acts as a growth factor through paracrine/autocrine-mediated mechanisms." (PMID 36232554, 2022). "GHRH antagonists have been shown to inhibit cell cycle progression in several cancers by upregulating p21 and p27 while downregulating cyclins." (PMID 40244089, 2025). "Further research is required to explore the potential effects of GHRH antagonists on local GH production in lung tumors and other cancer types." (PMID 40244089, 2025). "Growth hormone-releasing hormone (GHRH) antagonists exert antitumor functions in different experimental cancers." (PMID 40244089, 2025). "Growth hormone-releasing hormone (GHRH) antagonists effectively inhibit the in vivo growth of various experimental cancers." (PMID 40255484, 2025). "Since the 1990s, the Schally group has focused their research on the role of growth hormone-releasing hormone (GHRH) in cancer, prompting efforts to develop synthetic antagonists of GHRH that can be used therapeutically." (PMID 40427140, 2025). "The presence of SV1 in several human cancer models provides a rationale for antitumor therapy based on the blockade of this receptor by specific GHRH antagonists." (PMID 39934495, 2025). "This aligns with previous findings showing that GHRH antagonists lower MYC expression in various experimental cancer models, including when combined with chemotherapy." (PMID 40244089, 2025). "In line with this, GHRH antagonists of the MIA class have been shown to impede cancer cell migration and invasion by preserving E-cadherin expression and inhibiting MMP2 and MMP9 expression and activity." (PMID 40244089, 2025). "We searched a series of anti-cancer drugs that, in combination with GHRH antagonists, can increase PCa/CRPC/NEPC cell death." (PMID 40427140, 2025). "Preclinical studies suggest GHRH antagonists as a low-toxicity cancer therapy, particularly in lung, prostate, breast, gastrointestinal cancers as well as acute myeloid leukemia and brain tumors." (PMID 40095316, 2025). "GHRH expression in cancers has led to the development of peptide antagonists (e.g., MIA-602 and -690) for therapeutic treatment." (PMID 40427140, 2025). "In the endeavor to explore novel methods for treatment of cancer and other malignancies, a large number of potent analogs of GHRH have been designed, synthetized, and developed." (PMID 39934495, 2025). "There is clear evidence in cell line and mouse models of PCa that targeting GHRH with peptide antagonists provides some anti-cancer efficacy." (PMID 40427140, 2025). "GHRHAnt oppose the growth factor activities of GHRH in malignancies and suppress cancers by blocking GHRHR/SVs activation." (PMID 38895505, 2024). "Predominantly, GHRH is produced in the hypothalamus, yet many peripheral tissues as well as several cancer lines and tumors have been shown to express GHRH." (PMID 39417961, 2024). "GHRH-Ants have been tested in cancers of varying origin and pathology, yet their potential in the treatment of AML, until recently, had been largely unexplored." (PMID 39417961, 2024).
cancer (continued). "Despite its discovery in tumoral productions hinting at its potential in the field of oncology, GHRH’s posited role in the development of cancer remained largely unexplored until the last few decades." (PMID 39417961, 2024). "With our extensive experience and interest in oncology, we turned our focus toward the synthesis of GHRH antagonists and their potential application in cancer therapy." (PMID 39592529, 2024). "GHRH antagonists can counteract those effects eliciting anti-inflammatory responses, which contribute to their anti-cancer activities." (PMID 38957466, 2024). "The anti-oncogenic mechanisms of GHRH antagonists are vast, and likely involve crosstalk between multiple biologic pathways dependent upon cancer type." (PMID 38588464, 2024). "When used in conjunction with other treatments, the synergistic effects highlight the potential of GHRH antagonists as adjuvant therapies in cancer treatment." (PMID 39592529, 2024). "In the past two decades, the function, potential role and expression of GHRH and its tumoral receptors were already investigated in various human cancers." (PMID 39201517, 2024). "Previous research has shown that MIA-602 and other GHRH antagonists can inhibit the growth, tumorigenicity, and metastases of various human experimental cancers by targeting GHRH-R." (PMID 37370714, 2023). "In previous studies, we have shown that the GHRH antagonist MIA-602 suppresses the growth of several distinct human cancer cell lines in both in vivo and in vitro models." (PMID 37370714, 2023). "We have previously produced nearly 2000 synthetic antagonistic analogues of GHRH, which have been shown to inhibit, with few adverse effects, the development of 60 human cancer cell lines xenografted into nude mice." (PMID 37370714, 2023). "Numerous human cancers have been shown to produce GHRH, which acts as a growth factor through an autocrine/paracrine mechanism." (PMID 37370714, 2023). "Previously, it has been shown that the use of growth hormone–releasing hormone (GHRH) antagonistic peptide analogs significantly suppresses the proliferation of various human cancer cell lines." (PMID 37370714, 2023). "Growth hormone-releasing hormone (GHRH) and its receptors are expressed in a variety of human cancers, and have been involved in malignancies." (PMID 36540765, 2022). "It is widely accepted that GHRH acts as an autocrine/paracrine regulator for cancer cell proliferation." (PMID 35566020, 2022). "Herein, we investigate the effect of a commercially available GHRH antagonist, namely JV-1–36, in the redox status of the A549 human cancer cell line." (PMID 36540765, 2022). "mRNAs encoding four SVs of GHRH-Rs, GHRH-R protein and specific high affinity binding sites for GHRH and its antagonistic analogs have been demonstrated in several experimental cancer models and specimens of human tumors." (PMID 35566020, 2022). "GHRH antagonists also reduced the expression of proteins involved in tumorigenesis and cancer progression, upregulated proapoptotic molecules, and lowered GHRH receptor levels." (PMID 34439107, 2021). "In fact, GHRH antagonists suppress the growth in vivo of many types of cancer, including breast, pancreatic and colorectal carcinomas, gastric and prostate cancer, lung carcinomas, malignant pleural mesotheliomas, and malignant glioblastomas." (PMID 34439107, 2021). "Despite exerting strong antitumor activity in a variety of human experimental cancers and possessing higher binding affinity for their receptors compared with earlier GHRH antagonists, MIA-602 and MIA-690 display a weak inhibitory effect on GH release." (PMID 34439107, 2021). "In agreement, a number of studies demonstrated that GHRH and GHRH antagonists can modulate the inflammatory and reduction/oxidation (redox) status in cancer and other tissues." (PMID 33510215, 2021).